MYO1A (myosin IA)
Description:
Involved in directing the movement of organelles along actin filaments.
Synonyms: BBMI; MIHC; MYHL; DFNA48; DIAR15
Tractability: Antibody: its Gene Ontology location is reachable by antibodies, with medium confidence. PROTAC: ubiquitination databases record sites on it.
Gene: Protein-coding gene on chromosome 12 (57,028,517 to 57,051,198, reverse strand). Ensembl gene ENSG00000166866.
Subcellular location: Cell projection, microvillus
Subcellular location (Human Protein Atlas): Nucleoplasm
Gene Ontology:
Molecular function: actin filament binding; ATP binding; cytoskeletal motor activity
Biological process: sensory perception of sound; vesicle localization; actin filament-based movement; endocytosis
Cellular component: apical plasma membrane; basolateral plasma membrane; brush border; cortical actin cytoskeleton; cytoplasm; filamentous actin; lateral plasma membrane; microvillus; actin cytoskeleton; plasma membrane; actin filament; basal plasma membrane; myosin complex; plasma membrane bounded cell projection; plasma membrane raft
Genetic constraint (gnomAD): Loss-of-function variants: 127 observed, 147.11 expected, observed/expected ratio (o/e) 0.86, 90% interval 0.75 to 1. The upper end of that interval is the gene's LOEUF score, 1, which puts it in group 4 of 6, group 1 being the genes least tolerant of losing a copy. Missense variants: 1,211 observed, 1,358.1 expected, observed/expected ratio (o/e) 0.89, 90% interval 0.85 to 0.94. Synonymous variants: 477 observed, 525.94 expected, observed/expected ratio (o/e) 0.91, 90% interval 0.84 to 0.98.
Gene-disease validity (ClinGen):
ClinGen rates the evidence that MYO1A causes each of these diseases.
nonsyndromic genetic hearing loss (autosomal dominant): Refuted.
Homologues: Orthologues: chimpanzee MYO1A (99% identical), macaque MYO1A (96% identical), dog MYO1A (89% identical), pig MYO1A (89% identical), rabbit MYO1A (88% identical), mouse Myo1a (88% identical), rat Myo1a (87% identical), guinea pig MYO1A (87% identical), tropical clawed frog myo1a (61% identical). Paralogues in human: MYO1B (59% identical), MYO1C (42% identical), MYO1H (39% identical), MYO1D (39% identical), MYO1G (38% identical), MYO7A (31% identical), MYO7B (30% identical), MYO10 (30% identical), MYH7 (30% identical), MYH10 (30% identical), MYH11 (30% identical), MYH6 (29% identical), and 32 more.
Diseases named in the same sentence as MYO1A in open-access papers:
MYO1A is named in the same sentence as 31 diseases in open-access papers, as found by Europe PMC text mining. Sharing a sentence is not in itself a finding about the gene and the disease. The quoted sentences say what the papers report.
deafness (5 papers, 2014 to 2025). An inherited or acquired condition characterized by the complete loss of the ability to hear from one or both ears. "Association of MYO1A variants with deafness was refuted as either the variants of MYO1A were identified in healthy controls or the deafness was explained by convincing variants of different genes." (PMID 40426046, 2025). "Association of variants of MYO1A with deafness was refuted as either the variants of MYO1A were identified in healthy controls or the deafness was explained by convincing variants of different genes." (PMID 38562617, 2024). "MYO1A, also known as “brush border myosin-I”, has been identified as a cause of deafness and had tumor suppressor activity in the intestine." (PMID 31766183, 2019). "To date, three genes encoding the class-I myosins, MYO1A, MYO1C and MYO1F, were initially reported as human “deafness genes”." (PMID 38562617, 2024). "Furthermore, disease alleles were observed for other autosomal dominantly inherited degenerative diseases of sensory function, including retinitis pigmentosa (SEMA4A, RP1), deafness (MYO1A), glaucoma (CYP1B1, OPTN, WDR36), and keratoconus (VSX1)." (PMID 25333069, 2014).
breast carcinoma (3 papers, 2021 to 2022). "Interestingly, as the entire myosin superfamily, its internal members have different roles in tumors; for example, MYO1A can inhibit gastrointestinal tumors, while MYO1E can promote breast cancer invasion." (PMID 34322156, 2021).
colorectal cancer (3 papers, 2015 to 2020). A primary or metastatic malignant neoplasm that affects the colon or rectum. "MYO1A had mutations and promoter hypermethylation in patients with colorectal cancer and gastric tumors; therefore, lower levels of MYO1A expression was associated with faster tumor progress and poor prognosis." (PMID 32998690, 2020). "In intestine Myo1a regulates polarization and differentiation of colorectal cancer cells, is mutated in colorectal cancers, and has tumor-suppressor activity suggesting that equally important physiological roles for Myo1b in humans will ultimately be found." (PMID 26361046, 2015).
hearing loss (3 papers, 2018 to 2025). "However, the role of MYO1A in the development of hearing loss remains uncertain." (PMID 40426046, 2025). "Gene Myosin IA (MYO1A) is located on ROH island on chromosome B4, and is expressed in the inner ear and is a candidate gene for hearing loss in human." (PMID 38540427, 2024).
colon cancer (2 papers, 2020 to 2021). "Brush border protein myosin Ia (MYO1A), which plays an essential role in polarization and differentiation in colon cancer, is highly expressed in normal gastric epithelial cells, suppressing intestinal tumors." (PMID 32174791, 2020).
diarrheal disease (1 paper, 2013). The condition of having at least three loose or liquid bowel movements each day. "For example, since Myo1a is an intestine-specific myosin, modulation of Myo1a may be useful in designing treatments for diarrheal diseases." (PMID 23644890, 2013).
escherichia coli infection (1 paper, 2021). Infection with the organism Escherichia Coli. "To illustrate the complex interplays of regulatory elements and gene expression with respect to Escherichia coli infection and microvillar membrane morphology in intestinal tissues, we present an analysis of Myosin 1A (MYO1A)." (PMID 34615879, 2021).
Obesity (1 paper, 2015). Accumulation of substantial excess body fat. "Thereby we identified a premature stop codon in MYO1A associated with higher hs-GH and lower measures of obesity as well as higher levels of HDL-C and one premature stop codon of ZNF77 associated with higher hs-GH and height." (PMID 26086970, 2015).
ovarian carcinoma (1 paper, 2025). A malignant neoplasm originating from the surface ovarian epithelium. "There is little evidence to link the OR2T35 or MYO1A to the biology of ovarian cancer." (PMID 39939714, 2025).
stomach adenocarcinoma (1 paper, 2023). "MYO1A is most highly expressed in the digestive tract, and it is associated with stomach adenocarcinoma and colon cancer." (PMID 36759514, 2023).
tumor (11 papers, 2014 to 2025). "The loss of another component of microvilli i.e. myosin-Ia results in tumor development, loss of IECs polarity, and carcinogenesis in mice." (PMID 35507857, 2022). "The loss of MYO1A contributes to the reorganization of the actin cytoskeleton and the dedifferentiation of intestinal epithelial cells, leading to tumor progression." (PMID 32670437, 2020). "It was previously reported that myosin Ia possesses the capacity for tumor suppression through its regulation of the polarization and differentiation of colorectal cancers." (PMID 27283888, 2016). "Six genes were found to be altered in two tumours: MYO1A, DNAH11, SH2D5, ATM, MUC4 and ROS1." (PMID 29665859, 2018). "Although MYO1A may help maintain epithelial cells and play a role in suppressing cancer, other type I myosins that promote cell movement, such as MYO1E, may be related to tumor cell dedifferentiation and metastasis." (PMID 32670437, 2020).
infection (1 paper, 2023). The state of being infected such as from the introduction of a foreign agent such as serum, vaccine, antigenic substance or organism. "On the other hand, the downregulation of jhamt in adult midgut enterocytes using Myo1A-Gal4ts driver, did not significantly affect egg laying or survival to infection." (PMID 36984780, 2023).
MYO1A also shares sentences with these, for which no sentence is quoted: cancer (6 papers); cardiovascular disease (1); cervical adenocarcinoma (1); colorectal tumors (1); degenerative diseases (1); gastric tumors (1); gastrointestinal tumors (1); glaucoma (1); head and neck cancer (1); head and neck squamous cell carcinoma (1); hepatoma (1); Insulin resistance (1); intestinal tumors (1); keratoconus (1); lung adenocarcinoma (1); Perrault syndrome (1); retinitis pigmentosa (1); serous ovarian cancer (1); Usher syndrome type IIA (1).